ATXN3 (ataxin 3)
Diseases named in the same sentence as ATXN3 in open-access papers (continued):
Sharing a sentence is not in itself a finding about the gene and the disease.
Spinocerebellar ataxia type 3 (continued). "Expansion of a polyglutamine (polyQ) tract in ataxin-3 causes the dominantly inherited neurodegenerative disease, Spinocerebellar Ataxia Type 3 (SCA3) or Machado-Joseph Disease (MJD)." (PMID 20865150, 2010). "Spinocerebellar ataxia type 3 (SCA3) is a rare neurodegenerative disorder caused by the expansion of a polyglutamine (polyQ) repeat in ataxin-3 (Atx3) for which no disease-modifying therapies are available." (PMID 41306023, 2025). "Spinocerebellar ataxia type 3 (SCA3), also known as Machado-Joseph disease (MJD), is the most common autosomal dominant ataxia worldwide and is caused by the expansion of a CAG repeat in the ATXN3 gene." (PMID 38227368, 2024). "In Machado-Joseph disease (MJD), also known as spinocerebellar ataxia type 3 (SCA3), the affected protein ataxin-3 is characterized by a pathological expansion of a C-terminally located polyglutamine (polyQ) stretch, encoded by a CAG repeat in the ATXN3 gene." (PMID 37273907, 2023). "Spinocerebellar ataxia type 3 (SCA3), or Machado-Joseph disease (MJD), is known as the most common autosomal dominant hereditary ataxia, which is caused by abnormal and unstable expansion of a CAG repeat sequence in the ATXN3 gene." (PMID 37438701, 2023). "Spinocerebellar ataxia type 3 (SCA3), also known as Machado-Joseph Disease, is a progressive neurodegenerative disorder characterized by loss of neuronal matter due to the expansion of the CAG repeat in the ATXN3/MJD1 gene and subsequent ataxin-3 protein." (PMID 35558088, 2022). "In animal models of spinocerebellar ataxia type 3 (SCA3) and Alzheimer's disease (AD), UBE4B facilitates clearance of ataxin 3 and APP, respectively." (PMID 36440598, 2022). "Machado-Joseph disease (MJD), or spinocerebellar ataxia type 3 (SCA3), is a neurodegenerative disorder caused by an expansion in the number of CAG repeats in the ATXN3/MJD1 gene resulting in an expanded polyglutamine tract in the ataxin-3 protein." (PMID 32867861, 2020). "Spinocerebellar ataxia type 3 (SCA3), also called Machado–Joseph disease (MJD), is a dominantly inherited genetic disease resulting from the special type of mutation–expansion of CAG repeats in the ATXN3 gene (MJD and ATXN3: OMIM 109150 and 607047)." (PMID 31201651, 2019). "Machado-Joseph disease, also known as spinocerebellar ataxia type 3 (SCA3/MJD), is anautosomal dominant spinocerebellar ataxia caused by an expanded CAG repeat (longerthan 51 triplets) at ATXN3 gene, giving rise to an expandedpolyglutamine (polyQ) at ataxin-3 protein (Saute andJardim, 2015)." (PMID 31188927, 2019). "Rather, our findings in FUS-linked ALS are consistent with previous work performed in a Drosophila model for spinocerebellar ataxia type 3, in which overexpression of MBNL1-enhanced ataxin-3 induced neurodegeneration." (PMID 31811140, 2019). "In spinocerebellar ataxia type 3 (SCA3), the co-chaperone DnaJ homology subfamily B member 1 (DNAJB1 or heat shock protein 40) is recruited to protein aggregates formed by the disease-causing mutant polyglutamine (polyQ) protein ataxin-3 (ATXN3)." (PMID 30086154, 2018). "Spinocerebellar ataxia type 3 (SCA3), like OPMD, is a trinucleotide repeat neurodegenerative disease caused by the polyglutamine (versus polyalanine) expansion in the deubiquitinating enzyme, Ataxin-3 (ATXN3)." (PMID 26527730, 2016). "As a deubiquitinating enzyme (DUB), the physiological substrates of ataxin-3 (ATX-3) remain elusive, which limits our understanding of its normal cellular function and that of pathogenic mechanism of spinocerebellar ataxia type 3 (SCA3)." (PMID 27851749, 2016). "Machado-Joseph disease (MJD) or Spinocerebellar Ataxia type 3 (SCA3) is the most common dominantly inherited SCA worldwide and is caused by the expansion of a polyQ tract in the C-terminus of the ATXN3 gene product." (PMID 26505994, 2015).
Spinocerebellar ataxia type 3 (continued). "Spinocerebellar ataxia type 3 (SCA3), also known as Machado-Joseph Disease (MJD), is an autosomal dominant neurodegenerative disorder caused by a CAG-trinucelotide repeat expansion within the coding region of the ATXN3 gene (also called the MJD1 gene)." (PMID 23382971, 2013). "Machado-Joseph disease (MJD) or Spinocerebellar Ataxia type 3 is caused by a polyglutamine-encoding CAG expansion in the ATXN3 gene, which encodes a 42 kDa deubiquitinating enzyme (DUB), ataxin-3." (PMID 22970133, 2012). "Spinocerebellar ataxia type 3 (SCA3), also named Machado–Joseph disease (MJD), is an autosomal dominant cerebellar ataxia associated with the expansion of the ATXN3 exon 10 CAG repeat to 45 copies or more, resulting in a mutant ataxin-3 protein with an expanded poly-glutamine (polyQ) tract." (PMID 32357546, 2020). "Spinocerebellar ataxia type 3 (SCA3), known as Machado-Joseph disease, is one of nine polyglutamine (polyQ) diseases that occurs due to an abnormal expansion of polyglutamine in exon 10 of the ATXN3 gene." (PMID 28676741, 2017). "Spinocerebellar ataxia type 3 (SCA3), commonly known as Machado–Joseph disease, is an autosomal dominant neurodegenerative ataxia initiated by expanded cytosine–adenine–guanidine (CAG) triplet repeats in the coding region of ATXN3, specifically located at chromosome 14q32.1." (PMID 38539908, 2024). "Dominant inheritance of mutant Ataxin-3 (ATX3) leads to neurodegenerative disorder Machado-Joseph disease (MJD1, also known as spinocerebellar ataxia type 3/SCA3), with abnormal expansion of its C terminal polyglutamine (polyQ) repeats up to 55–87 in comparison to 10–51 in healthy individuals." (PMID 33425926, 2020). "Recently, treatment of a C. elegans model of SCA3 (spinocerebellar ataxia type 3; also known as Machado-Joseph disease) with 17-(allylamino)-17-demethoxygeldanamycin (17-AAG), an HSP90 inhibitor, successfully decreased the mutant ATXN3 aggregation and improved locomotor activity." (PMID 26617668, 2015).
Ataxia (167 papers, 2009 to 2026). Ataxia refers to impaired coordination of voluntary muscle movement. "MJD/SCA3, the most common form of dominant Spinocerebellar Ataxia worldwide, is caused by an expansion of the polyglutamine tract within the ataxin-3 protein, and is characterized by motor impairments." (PMID 38404918, 2024). "SCA3 is the most common form of spinocerebellar ataxia worldwide, caused by a polyglutamine (polyQ) repeat at the Ataxin-3 (ATX3) C-terminus." (PMID 39063148, 2024). "Machado–Joseph disease (MJD) is an autosomal dominant neurodegenerative spinocerebellar ataxia caused by a polyglutamine-coding CAG repeat expansion in the ATXN3 gene." (PMID 39088078, 2024). "Two are in genes associated with spinocerebellar ataxia (ATXN3, ATXN7), while one is in FAM3A, encoding a cytokine-like protein that has been associated with modulation of PI3K signalling." (PMID 37974153, 2023). "Whereas normal alleles possess 12–43 repeats, pathogenic ATXN3 alleles contain 60–87 repeats with milder forms of ataxia and restless leg syndrome appearing in patients with mid-range repeats." (PMID 36187346, 2022). "It is caused by the expansion of a CAG repeat in the ATXN3 gene, leading to a slowly progressive cerebellar ataxia with other various symptoms." (PMID 35865750, 2022). "The transgenic mice used in these experiments express only a truncated C-terminal fragment of mutant ataxin-3, opening the possibility for this mouse model to represent a wider model of polyQ-associated spinocerebellar ataxias." (PMID 33558582, 2021). "SCA3 is the most common of the dominantly inherited ataxias and is caused by a CAG repeat expansion in the ATXN3 gene." (PMID 29929540, 2018). "SCA3, also known as Machado–Joseph disease, is the most common inherited ataxia that is also caused by CAG expansion in the deubiquitinase ataxin-3, coded by the ATXN3 gene." (PMID 29867345, 2018). "Extensive repeats in exons of ATXN3 would affect pons and striatum, causing progressive cerebellar ataxia and even paralysis." (PMID 28720120, 2017). "Machado Joseph Disease (MJD) is the most frequent autosomal dominantly inherited cerebellar ataxia caused by the over-repetition of a CAG trinucleotide in the ATXN3 gene." (PMID 27328712, 2016). "SCA3 is the most common inherited ataxia and is caused by a CAG repeat expansion in the ATXN3 gene." (PMID 34160773, 2021). "Importantly, polyglutamine repeat mutations in ataxin-3 are themselves associated with the spinocerebellar ataxia Machado-Joseph disease." (PMID 31379806, 2019). "Indeed, Ataxin-1, as well as another ataxia-associated protein, Ataxin-3, have been linked to the retinoic acid-related orphan nuclear receptor alpha (RORα) pathway, which is critical for cerebellar development." (PMID 26136256, 2015). "However, we have termed a subset of ataxias, not just with reduced IP3R1 but also with supersensitive IP3R1, and regardless of the mutated gene (e.g., ITPR1, Ataxin-1, Ataxin-2, Ataxin-3) as ‘IP3R1-associated ataxias’." (PMID 22703638, 2012). "Many forms of spinocerebellar ataxia, which are among the most common hereditary ataxias, are caused by trinucleotide repeat expansions in several genes (FXN, ATXN1, ATXN2, ATXN3)." (PMID 41010014, 2025). "SCA3 is the most common of the family of neurodegenerative diseases known as spinocerebellar ataxias and is caused by an expansion of the polyglutamine (polyQ) repeat region, encoded by predominantly CAG trinucleotide repeats in ATXN3." (PMID 40963374, 2025). "ATXN3 has been extensively studied for decades as the protein causing SCA3, the most common inherited ataxia worldwide." (PMID 39320846, 2024). "SCA3, caused by an expanded CAG repeat in the ATXN3 gene, is one of the most common dominantly inherited ataxias worldwide and is characterized by cerebellar degeneration and progressive ataxia." (PMID 37664882, 2023).
Ataxia (continued). "In a previous natural history study, female ATXN3 carriers were found to have a faster progression in the number of non‐ataxia signs compared to males." (PMID 35478426, 2022). "The frequency is followed by ATXN7: 6.09%, TBP: 5.59%, ATXN2: 5.03%, CACNA1A: 4.28%, PPP2R2B: 2.68%, and ATXN3: 2.42% with respective cutoff values in uncharacterized ataxia cases." (PMID 36618024, 2022). "Specifically, Ataxin-10 (ATX10) and Ataxin-3 (ATX3) are both responsible for different forms of spinocerebellar ataxia in humans, a type of neurodegenerative disease." (PMID 35482036, 2022). "SCA3 is most common dominant ataxia worldwide and the causative mutation is an expanded CAG repeat in the ATXN3 gene." (PMID 30430184, 2019). "Spinocerebellar ataxia (SCA) type 2 and 3 are caused by cytosine–adenine–guanine (CAG)n repeat expansions in ATXN2 and ATXN3 genes (OMIM 601517, 607047), which are the most common types of SCAs in China." (PMID 30920184, 2019). "We also demonstrated that neural differentiation was accompanied by autophagy and that rapamycin promoted autophagy, which resulted in degradation of mutant ATXN3 in neurally differentiated spinocerebellar ataxia-3 human iPS cells." (PMID 27847820, 2016). "In fact, Uchl1, Otub1 and Atxn3 are involved in neurodegenerative diseases in human, namely Parkinson's disease and cerebellar ataxia, thus indicating a relevant role in neurodegeneration." (PMID 26934049, 2016). "This disease is one of the most common dominantly inherited ataxias worldwide; the defect in SCA3 is due to CAG repeat expansion (from the normal 14–41 to 55–82 repeats) in the ATXN3 coding region." (PMID 25633985, 2015). "SCA3/MJD, which is the most common dominantly inherited ataxia in China and other countries, is caused by an unstable CAG trinucleotide repeat expansions in the ATXN3 gene." (PMID 26083476, 2015). "Apart from key ataxia proteins like ataxin-1 or ataxin-3, this degradation also includes proteins involved in motor neuron disease such as SOD1 proteins." (PMID 24742043, 2014). "Machado–Joseph disease (MJD) is the most common dominant inherited ataxia worldwide, caused by an unstable CAG trinucleotide expansion mutation within the SCA3 gene resulting in an expanded polyglutamine tract within the ataxin-3 protein." (PMID 23653622, 2013). "In conclusion, we have developed and characterized an AAV-based mouse model of SCA3 that exhibits ataxia-like defects in locomotor behavior, mutant ATXN3 and pTDP-43 inclusion pathology, cerebellar-specific neuronal degeneration, elevated CSF NFL levels, and increased plasma polyQ-ATXN3 levels." (PMID 35386195, 2022). "The accelerator effect of the expanded CAG repeat of ATXN3 on ataxia progression may only exist in certain populations." (PMID 35865750, 2022). "The finding of the accelerator effect of the expanded CAG repeat of ATXN3 on ataxia progression could facilitate the patient stratification in future SCA3 trials in Mainland China." (PMID 35865750, 2022). "Combination of early and autonomic abnormalities and ataxia would be more characteristic of the cerebellar type of multiple system atrophy (MSA-C), the patient's positive family history and identification of an ATXN3 gene mutation supported SCA3 diagnosis." (PMID 36237609, 2022). "Additionally, polyQ-expanded ataxin-3 protein levels correlated with disease progression and clinical severity as assessed by the Scale for the Assessment and Rating of Ataxia." (PMID 33106888, 2021). "Ataxin 3 (ATX3) is involved in protein ubiquitination, a trinucleotide expansion of this gene (CAG) causes Machado-Joseph disease or spinocerebellar ataxia, although this mutation is associated with neuronal death, so far ATX does not have a well-defined role in brain development." (PMID 32879369, 2020).
Ataxia (continued). "Spinocerebellar ataxia-3 (SCA3) is the most common dominant inherited ataxia worldwide and is caused by an unstable CAG trinucleotide expansion mutation within the ATXN3 gene, resulting in an expanded polyglutamine tract within the ATXN3 protein." (PMID 27847820, 2016). "A national survey conducted to establish the epidemiological profile of inherited ataxias in this island identified a reduced frequency of ATXN3 gene in the Cuban population with autosomal dominant cerebellar ataxias, whereas the molecular and clinical data were not provided." (PMID 26331044, 2015). "Therefore, we can assume that changes in the amino acid structure of ITPR1 may indirectly affect the activity of VCP or ATXN3, which may contribute to the development of a neurodegenerative process in this type of ataxia." (PMID 26770814, 2016). "Furthermore, we demonstrated that neural differentiation in these iPS cells was accompanied by autophagy and that rapamycin promoted autophagy through degradation of mutant ATXN3 proteins in neurally differentiated spinocerebellar ataxia-3 human induced pluripotent stem cells (p < 0.05)." (PMID 27847820, 2016). "This study involved six genes (ATXN1, ATXN3, ATXN7, HTT, NOP56, and PPP2R2B), while a higher detection rate has been reported in a spinocerebellar ataxia cohort (4.4%, 22/498), which included five genes (ATXN2, ATXN3, NOP56, AR and HTT)." (PMID 38308084, 2024). "In patients with cerebellar signs, 6 of 9 were screened for the common spinocerebellar ataxia genes including ATXN1 (SCA 1), ATXN 2 (SCA2), ATXN3 (SCA3) and ATXN7 (SCA7)." (PMID 39113437, 2024). "SCA3 arises from an expanded CAG repeat (CAGexp) in ATXN3 gene, which is hallmarked by progressive cerebellar ataxia and variable features including pyramidal syndrome, extrapyramidal signs as well as peripheral neuropathy." (PMID 35568848, 2022). "For ataxias SCA1, SCA2, SCA3, SCA6, SCA7, SCA17 and dentatorubral-pallidoluysian atrophy, expansion beyond 39, 33, 45, 20, 34, 41, and 35 repeats in the ATXN1, ATXN2, ATXN3, CACNA1A, ATXN7, TBP, and ATN1 genes, respectively, will cause disease." (PMID 35592702, 2022). "Further, mutant ATXN3 was not identified as a predictor of ataxia progression." (PMID 40411538, 2025). "Our novel observation that DNAJA3 shows significantly enriched interaction with disease proteins that are responsible for spinocerebellar ataxia, including the nuclear transcription modulator ATXN1 or the cytosolic stress response factor ATXN3, might be viewed in this context." (PMID 34345994, 2021). "However, BBB integrity has not been assessed in spinocerebellar ataxias (SCAs) such as Machado-Joseph disease/SCA type 3 (MJD/SCA3), a genetic disorder, triggered by polyglutamine-expanded ataxin-3." (PMID 32867861, 2020).